HMGB1P23 (high mobility group box 1 pseudogene 23)
Gene: Processed pseudogene on chromosome 8 (29,218,905 to 29,219,472, forward strand). Ensembl gene ENSG00000253770.
Diseases named in the same sentence as HMGB1P23 in open-access papers:
HMGB1P23 is named in the same sentence as 1 disease in open-access papers, as found by Europe PMC text mining. Sharing a sentence is not in itself a finding about the gene and the disease. The quoted sentences say what the papers report.
nasopharyngeal carcinoma (1 paper, 2025). A carcinoma arising from the nasopharyngeal epithelium. "Although members of the high-mobility group box family have been implicated in carcinogenesis (e.g., high expression of HMGB1 in human nasopharyngeal carcinoma) and autoinflammatory diseases, no published literature exists on diseases or disorders specifically associated with HMGB1P23." (PMID 40160448, 2025).